IL1R1 (interleukin 1 receptor type 1)
Diseases named in the same sentence as IL1R1 in open-access papers (continued):
Sharing a sentence is not in itself a finding about the gene and the disease.
cognitive deficits (19 papers, 2017 to 2025). "Accordingly, SARS-CoV-2, but not H1N1 influenza virus, increases levels of brain IL-1β and induces persistent IL-1R1-mediated loss of hippocampal neurogenesis, which promotes post-acute cognitive deficits." (PMID 37790551, 2023). "Here, we performed behavioral tests to examine cognitive impairment, with the finding that SE mice showed significant cognitive decline, while deletion of endothelial IL-1R1 alleviated impaired spatial memory." (PMID 38087170, 2024). "Microglia/monocyte signaling to endothelia IL-1R1 elicits anxiety-like behavior and neuronal IL-1R1 mediates social withdrawal and cognitive impairment." (PMID 38459193, 2024). "Previous studies have shown that IL-1R1 KO mice exhibit reduced cognitive deficits in the Morris water maze at 3-months post-injury in a single CHI model, and at 6 months post-injury in a repetitive CHI model." (PMID 37884959, 2023). "In this study, rats with CLP exhibited cognitive deficits 24 h after surgery, as well as severe inflammation in the CNS, manifested as increased expression of IL‐1R1, pNF‐κB, TNF‐α, and iNOS in microglial cells." (PMID 34837343, 2022). "In line with upregulated IL‐1β in CMECs, microglial cells were activated through IL‐1R1/pNF‐κB pathway and resulted in neuroinflammatory response and cognitive impairment." (PMID 34837343, 2022). "Furthermore, an important role for the IL-1/IL-1R1 signaling axis in driving TBI-induced cognitive deficits has been reported." (PMID 38685031, 2024). "Interestingly, we found that AβOs failed to cause cognitive impairment in Il1r1−/− mice and that anakinra attenuated alterations in the levels of mitochondrial proteins induced by AβOs in vitro." (PMID 33612100, 2021).
Anxiety (16 papers, 2014 to 2025). Intense feelings of nervousness, tension, or panic often arise in response to interpersonal stresses. "Stress, a critical trigger to induce anxiety, causes microglia to recruit a large number of monocytes into the brain parenchyma and promotes the synthesis of IL-1 receptor 1 (IL-1R1) in the vascular endothelium." (PMID 36051441, 2022). "Residential microglias secrete more IL-1β and bind to IL-1R1 in the vascular endothelium to mediate anxiety-like behaviors." (PMID 36051441, 2022). "Some studies have demonstrated that the suppression or ablation of IL1R1 has a reparative role against neurotoxicity and that it prevents the development of anxiety-like behavior in mice." (PMID 32531902, 2020). "For instance, interleukin (IL)-1β is associated with stress-induced macrophage recruitment and heightened anxiety-like behavior in males, and female rats exhibit greater basal IL-1β and IL1r1 expression in cortical and hippocampal tissue compared to males." (PMID 29194444, 2017). "In this study, blockade of macrophage influx in the amygdala by CCR2 and IL-1R1 inhibition prevented pain-induced anxiety-like behavior." (PMID 25653581, 2014). "Depleting of microglia with minocycline, or knockdown of IL-1R1, could reverse anxiety-like behavior." (PMID 36051441, 2022). "Potential sources include leukocytes that may have infiltrated into the brain, microglia, astrocytes and neurons, with IL-1β produced from such cells interacting with IL-1R1 on neurons involved in the anxiety circuits and behaviors observed in the current study." (PMID 35379260, 2022). "Moreover, IL-1 receptor type-1 (IL-1R1)-knockout mice do not exhibit stress-induced brain-monocyte trafficking, and this was also associated with the absence of anxiety-like behavior." (PMID 25653581, 2014). "In agreement, endothelial IL‐1R1 knockdown mice did not develop anxiety following RSD stress paradigm." (PMID 31421056, 2021).
psoriasis (16 papers, 2016 to 2025). An autoimmune condition characterized by red, well-delineated plaques with silvery scales that are usually on the extensor surfaces and scalp. "Furthermore, IL-1R1 blockade was found to alleviate psoriatic skin inflammation, decrease Cxcl2 expression, and diminish neutrophilia, suggesting that IL-1β dysregulation due to autophagy deficiency plays an important role in psoriasis pathogenesis by driving neutrophilic inflammation." (PMID 38704587, 2024). "Mice were systemically administered anti-IL-1R1 antibody, which blocks the interaction of IL-1β with its cognate receptor IL-1R during the development of psoriasis." (PMID 38704587, 2024). "We previously found that both IL-1R1 and IL-36α are important for the development of psoriasis-like skin inflammation in the imiquimod model; thus, we next examined their role in systemic disease." (PMID 28057979, 2016). "Moreover, IL-1β synergizes with IL-23 to activate IL-17 A-producing γδ T cells, a major contributor to psoriasis, and the IL-1β–IL-1R1 signalling pathway plays a crucial role in the pathogenesis of psoriasis." (PMID 38704587, 2024). "Although IL1Ra-deficient BALB/c mice have features in common with psoriasis, mice deficient in IL1R1 and IL-1RAcP have no obvious skin abnormalities, suggesting that the IL38/IL-1R1 axis might not be involved in the pathogenic mechanism of psoriasis." (PMID 31387327, 2019). "We investigated the recruitment of neutrophils and their expression of IL-1β in the IMQ-induced murine model of psoriasis in the presence or absence of anti-IL-1R1 antibody injection." (PMID 38704587, 2024). "The increase in IL-1R-1 in PS+T+EPA was not expected since studies have shown that this receptor was strongly activated in psoriasis-like skin inflammation in an imiquimod-induced mouse model." (PMID 37597582, 2023). "Moreover, IL-1R1 blockade significantly reduced the population of IL-17 A-producing γδ T cells, CD4+ T cells, and CD8+ T cells, consistent with the role of IL-1β in the development of IL-17 A-producing T cells and psoriasis pathogenesis." (PMID 38704587, 2024).
gout (14 papers, 2013 to 2025). A condition characterized by painful swelling of the joints, which is caused by deposition of urate crystals. "However, we reported that mice deficient for the IL-1 receptor IL-1R1 develop reduced but still significant ankle swelling as compared to WT mice in this acute gout model." (PMID 28982129, 2017). "In eQTL analysis, rs9973741 (allele G, which is the risk allele for gout) associated with decreased expression of IL1RN in the prostate and decreased expression of both IL1RN and IL1R1 in whole blood, while increasing IL1RN expression in the testes." (PMID 40385401, 2025). "LocusZoom plots were generated for each SNP that significantly contributed to the positive association between gout and prostate cancer, and each SNP was assigned to the closest gene: SLC30A5 (rs2560449), IL1R1 (rs17767183), IL1RN (rs9973741)." (PMID 40385401, 2025). "Our MR study identified three genes driving the relationship between the non-hyperuricemia compartment of gout and prostate cancer: IL1R1 (rs17767183), IL1RN (rs9973741), and SLC30A5 (rs2560449)." (PMID 40385401, 2025).
diabetes (13 papers, 2015 to 2025). "Future studies utilizing T2DM models combined with controlled disc injury or aging models are essential to conclusively establishing the mechanistic link and causal role of IL1R1 in driving diabetes-accelerated disc degeneration." (PMID 41169383, 2025). "IL1R1 was highly expressed in specific diabetes-associated NP subpopulations and showed significant positive correlation with neutrophil infiltration." (PMID 41169383, 2025). "Notably, its documented mechanism, antagonizing NF-κB and MAPK-mediated pro-inflammatory cascades, could be conceptually aligned with the IL1R1-driven pathology implicated in our study of diabetes-associated IDD." (PMID 41169383, 2025). "The area under the curve (AUC) values for S100A12, IL1R1, and FCGR2B were 0.744, 0.785, and 0.868, respectively, indicating robust diagnostic efficacy for diabetes-associated IDD." (PMID 41169383, 2025). "We have previously shown that diabetes leads to the activation of caspase-1 and IL-1β production and that blocking downstream caspase-1/IL-1β/IL-1R1 signaling using IL-1R1 knockout mice prevented the formation of acellular capillaries and Müller cell death." (PMID 39483336, 2024). "Using the IL-1R1−/− mice we identified that diabetes-induced caspase-1 activity progresses from an IL-1R1 independent mechanism to an IL-1R1 dependent mechanism throughout disease progression." (PMID 39483336, 2024). "These seemingly disparate roles of IL-1R1 signaling in increased myelopoiesis in different animal models of pre-diabetes and diabetes deserve further study." (PMID 32671072, 2020). "Analysis of immune cell infiltration for the key diabetes-disc degeneration gene IL1R1 revealed that IL1R1 expression exhibited a significant positive correlation with neutrophils, and a significant negative correlation with activated dendritic cells and activated natural killer cells." (PMID 41169383, 2025). "Our in vivo results demonstrate that caspase-1 activation progresses from an IL-1R1 independent mechanism at 10 weeks of diabetes to an IL-1R1 dependent mechanism at 20 weeks indicating that feedback through IL-1R1 is crucial for sustained caspase-1 activity in retinas of mice." (PMID 39483336, 2024). "Interestingly, several DEGs identified in this study had been reported to be associated with the occurrence and progression of diabetes, including SERPINF1, PID1, IL1R1 and PGC." (PMID 39845878, 2024). "Decorated with a high concentration of pattern recognition receptors, i.e., TLR3/4, RIG-I, MDA-5, and with IL-1R1, and especially vulnerable to inflammatory destruction, the β-cell undergoes apoptosis in response to inflammation, metabolic control derails and diabetes develops." (PMID 33162939, 2020). "In support of our data, it has been shown that anakinra, an inhibitor of IL-1R1-mediated signaling, is sufficient to inhibit several pathological features related to DN in a similar mouse model of diabetes, further underscoring the importance to target this axis for the treatment of DN patients." (PMID 27706238, 2016). "Our bioinformatics analysis implicates the IL1R1 gene as potentially exerting a profound influence on the occurrence and progression of IDD within the context of diabetes mellitus." (PMID 41169383, 2025). "Type 1 diabetes mellitus is another type of diabetes in which HLA (human lymphocyte antigen), IR1R1 (interleukin-1 receptor type 1), CTLA-4, and VDR are some important genes studied in association with T1DM." (PMID 26587547, 2015).
osteoarthritis (13 papers, 2010 to 2025). A noninflammatory degenerative joint disease occurring chiefly in older persons, characterized by degeneration of the articular cartilage, hypertrophy of bone at the margins and changes in the synovial membrane. "Another study involving the association between five SNPs polymorphisms in IL1R1 (rs10490571, rs12712127, rs956730, rs3917225, and rs3917318) and osteoarthritis risk, the result found that rs3917225 in IL1R1 was associated with increasing the risk of knee OA." (PMID 30623603, 2019). "MEDI8968 and AMG 108 are two fully humanized monoclonal antibodies targeting IL-1R1 that have been investigated for chronic obstructive pulmonary disease and osteoarthritis, respectively." (PMID 41390483, 2025). "For these reasons, inhibitors that target IL-1RAcP or interfere with its ability to bind the IL-1β/IL-1R1 binary complex may represent a new paradigm in osteoarthritis treatment." (PMID 33614593, 2020).
colorectal cancer (12 papers, 2016 to 2025). A primary or metastatic malignant neoplasm that affects the colon or rectum. "Here the authors identify a pro-tumorigenic CAF subtype in colorectal cancer characterized by high IL1R1 expression and associated with an immunosuppressive tumor microenvironment." (PMID 37460545, 2023). "This suggests that Anakinra’s target IL1R1 is stronger associated with extracellular matrix biology in colorectal cancer compared with the other cancer types." (PMID 27824868, 2016). "While IL1R1 perturbation has been shown to sensitize resistant tumors in a lung cancer model, myeloid-specific ablation of IL1R1 can promote colorectal cancer progression." (PMID 41305010, 2025). "In colorectal cancer, bacterial-driven inflammation and tumor development are reduced by the activation of the interleukin-1 receptor type 1 (IL-1R1) signaling pathway that takes place in neutrophils." (PMID 37444436, 2023). "Here we identify a pro-tumorigenic IL1R1+, IL-1-high-signaling subtype of fibroblasts, using multiple colorectal cancer (CRC) patient single cell sequencing datasets." (PMID 37460545, 2023). "However, in the CPC-APC (CDX2Cre-Apcf/wt) colorectal cancer model, specific deletion of IL-1R1 in myeloid cells (CD11bCre-Il1r1f/f) resulted in a higher tumor load and stronger inflammatory responses, such as increased IL-17A expression." (PMID 40767963, 2025). "As mentioned, IL-1 is also emerging as a cytokine involved in drug resistance; we recently reported that increased levels of tumor-derived IL-1 are correlated with cetuximab resistance in colorectal cancer xenopatients and that abundance of IL-1R1 is predictive of therapy response." (PMID 32825489, 2020). "IL1R1 was notable for its seemingly strong association with the ECM module in colorectal cancer but not in the other cancer types." (PMID 27824868, 2016). "Colorectal cancer patients who did not respond to Cetuximab blockage had higher levels of IL1R1 than responsive subjects, and high levels of IL1R1 are predictive of survival." (PMID 39190284, 2024). "We found the IL1R1-ECM correlation to be specifically increased in colorectal cancer (Pearson coefficient 0.74 on average) compared with non-colorectal datasets (0.3 on average, P < 10−6 in Mann-Whitney test)." (PMID 27824868, 2016).
viral infection (12 papers, 2011 to 2025). "Whereas, the viral infection in IL-1β receptor-I deficient (IL-1R1-/-) or IL-1R antagonist (IL-1Ra) treated mice, show reductions in virus replication, disease progress and mortality." (PMID 26367131, 2015). "Collectively, these data demonstrate a role for lung resident cells in promoting smoke-induced inflammation and support a role for the IL-1R1 in the differential response of the smoke-exposed lung to viral infection." (PMID 22163019, 2011). "Taken together, these data suggest that an IL-1R1 dependent mechanism contributes to exacerbation of the inflammatory response in smoke-exposed mice following viral infection." (PMID 22163019, 2011). "Accordingly, Il1r1−/− mice demonstrated both a deficiency in neutrophil recruitment to infected bite sites and were not susceptible to bite-mediated enhancement of virus infection, identifying this pathway as a putative therapeutic target." (PMID 27332734, 2016). "Therefore, in response to MHV-3 viral infection, IL-1R1-/- mice responded with limited fibrinogen formation, leading to a down modulation of liver coagulation and necrosis." (PMID 26367131, 2015). "The results of our study demonstrate the importance of IL-1α and its cognate receptor, IL-1R1, to the induction of cigarette smoke-induced airway inflammation, and to the exacerbation of inflammatory processes following viral infection of smoke-exposed animals." (PMID 22163019, 2011). "Interestingly, IL-1R1-/- mice displayed with a significant increase in survival rate with 60% staying alive for 20 days, as compared to a 100% death of the WT littermates within 5 days of the viral infection." (PMID 26367131, 2015). "In contrast to IFN-γ treatment, we here showed that the expression of Bgp1 drops significantly in the IL-1R1-/- liver during the viral infection, suggesting Bgp1 expression in macrophages is induced by IL-1β/IL-1R1 signaling, and lacking the pathway may compromise virus entrance and amplification." (PMID 26367131, 2015).
fungal infections (11 papers, 2011 to 2025). "While our studies and the studies just discussed strongly support a role for IL-1RI signaling in limiting IPA, and other invasive fungal infections, Romani and colleagues have observed that Il1r1-deficient mice were more resistant to pulmonary A. fumigatus challenge." (PMID 25629406, 2015). "Similarly, IL-1R1, which has been shown to be essential for the induction of Th17 cells in different microbial or non-microbial models, was found here to be dispensable for inducing Tc17 and controlling fungal infection in vaccinated CD4+ T-cell deficient hosts." (PMID 22829762, 2012). "Taken together these data suggest that IL-1R1-/- neutrophils exhibit reduced viability and increased apoptosis during fungal infection, which may contribute to reduced ability to control airway infection." (PMID 34322116, 2021). "Our discovery that Il-1r1-/- mice were more resistant than WT to B. pseudomallei infection is quite surprising considering that this cytokine has been shown to be protective in several bacterial, viral, and fungal infection models." (PMID 22241982, 2011).
Hepatic steatosis (11 papers, 2013 to 2024). Steatosis is a term used to denote lipid accumulation within hepatocytes. "Furthermore, in other studies, IL1-R1 and IL-1β knockout mice display attenuated hepatic steatosis and inflammation when exposed to alcohol and high cholesterol diet." (PMID 24146946, 2013). "In summary, blocking the IL-1R1 signaling pathway in hepatocytes not only improves the MASLD phenotype and insulin resistance, as previously demonstrated but also significantly slows hepatocarcinogenesis in the context of hepatic steatosis." (PMID 39621069, 2024).
inflammatory bowel disease (11 papers, 2009 to 2025). A spectrum of small and large bowel inflammatory diseases of unknown etiology. "Interleukin-1 and its receptor encoded by the IL1R1 gene regulate progression from liver injury to fibrosis; IL1R1 polymorphism is associated with the risk for inflammatory bowel disease." (PMID 25918251, 2015). "Nonetheless, we were intrigued about the augmented levels of Il17a and Il1r1 transcripts found in cluster 3 RORγtS182A colonic Th17 cells, as the elevated IL-1β level was associated with increased disease severity in patients with inflammatory bowel diseases." (PMID 35294872, 2022). "Similarly, IL1R1 is associated with RA and other inflammatory bowel diseases." (PMID 40839671, 2025). "Scarpa et al42 reported that fibroblasts isolated from inflammatory bowel disease tissue expressed IL-1R1, as did intestinal subepithelial fibroblasts in the intestine of mice challenged with a low dose of dextran sulfate sodium." (PMID 29248462, 2018). "Recent studies revealed that IL1R1 expression was observably increased in several types of disease, including knee osteoarthritis, Prostate Carcinoma, hand osteoarthritis and Inflammatory Bowel Disease." (PMID 28881593, 2017). "Patients with inflammatory bowel disease also exhibited an increase in NRG1+IL1R1+ fibroblasts and an interaction of NRG1–ERBB between IL1R1+ fibroblasts and colonic epithelial cells." (PMID 38674054, 2024).